NEAT1 (nuclear paraspeckle assembly transcript 1)
Diseases named in the same sentence as NEAT1 in open-access papers (continued):
Sharing a sentence is not in itself a finding about the gene and the disease.
iron overload (1 paper, 2025). "We found that PBMC NEAT1 and plasma iron levels were significantly and positively correlated with the Gensini scores of CHD patients (NEAT1: r = 0.4537, p < 0.0001; iron: r = 0.4264, p < 0.0001), suggesting that NEAT1 upregulation and iron overload are associated with AS." (PMID 41268533, 2025).
Kawasaki disease (1 paper, 2023). A rare inflammatory disease characterized by an acute febrile, systemic, self-limiting, medium-vessel vasculitis primarily affecting children. "In this study, the TOP4 lncRNAs common to most miRNAs were exhibited, the studies have found that The NEAT1/NORAD/XIST has-miR-204 axis regulates the development of Kawasaki disease (KD)." (PMID 37483435, 2023).
keloid (1 paper, 2021). An irregularly shaped, elevated mark on the skin caused by deposits of excessive amounts of collagen during wound healing. "The negative regulatory role of NEAT1 in keloid formation has also been reported." (PMID 34414852, 2021).
kidney failure (1 paper, 2025). An acute or chronic condition that is characterized by the inability of the kidneys to adequately filter the blood. "Furthermore, patients with kidney failure had an insignificantly lower expression of both MALAT1 (median: 0.32 vs. 0.40; p = 0.567) and NEAT1 (median: 0.34 vs. 0.40; p = 0.344)." (PMID 40150019, 2025).
lamellar ichthyosis (1 paper, 2023). A keratinization disorder characterized by the presence of large scales all over the body without significant erythroderma. "By analyzing probes matching specific NEAT1 long isoform in GEO datasets, we observed a significant increase of NEAT1_2 expression in samples derived from patients affected by Lamellar Ichthyosis." (PMID 37365156, 2023).
laryngeal papilloma (1 paper, 2022). "Long non-coding RNA nuclear-enriched abundant transcript 1 (Lnc-NEAT1) is a crucial mediator in cancer progression, which is associated with poor prognosis of patients with laryngeal papilloma (LP)." (PMID 35012431, 2022). "The aim of the present study was to explore the expression levels of Lnc-NEAT1, miR-577, miR-1224-5p and CCNT2 in LP, and to further investigate the potential underlying molecular mechanism by which they regulate the progress of laryngeal papilloma development." (PMID 35012431, 2022).
lentivirus infection (1 paper, 2020). Virus diseases caused by the Lentivirus genus. "First, we overexpressed or blocked lncRNA NEAT1/LATS2 by lentivirus infection." (PMID 32157157, 2020).
leukopenia (1 paper, 2022). "Our previous studies showed that CYP27A1 gene rs17470271 T; rs933994 T allele frequencies were respectively significantly related to leukopenia, drug resistance, and lncRNA NEAT1 gene rs3825071 TT genotype; T allele frequencies were significantly increased in sputum smear-positive PTB patients." (PMID 36275653, 2022).
male infertility (1 paper, 2025). The inability of the male to effect fertilization of an ovum after a specified period of unprotected intercourse. "And when integrated with NEAT1 and miR-34a biomarker, these findings may improve diagnostic accuracy and contribute to the development of treatment approaches for male infertility." (PMID 40165339, 2025). "The integration of serum NEAT1 and miR-34a in diagnostic approaches could be beneficial and extend the likelihood of identifying concrete causes of male infertility even more." (PMID 40165339, 2025).
malnutrition (1 paper, 2025). Inadequate nutrition resulting from poor diet, malabsorption, or abnormal nutrient distribution. "Additionally, LC patients with low MALAT1 expression had a significantly higher chance of developing severe malnutrition (p < 0.001), while those with low NEAT1 expression had an increased risk of moderate and severe malnutrition (p = 0.002)." (PMID 40150019, 2025). "Additionally, LC patients with low NEAT1 expression had more than a 13-fold higher probability of mild or severe malnutrition according to the SGA (OR = 13.09; p = 0.002) and an 11-fold higher chance of losing >5% of their body weight after RT (OR = 11.0; p = 0.026)." (PMID 40150019, 2025).
membranous nephropathy (1 paper, 2019). "The expression of lncRNAs XIST and NEAT1 are significantly increased in glomerular and tubular epithelial cells, and urinary XIST serves as a potential marker for detecting membranous nephropathy." (PMID 31658856, 2019).
mesothelioma (1 paper, 2020). A usually malignant and aggressive neoplasm of the mesothelium which is often associated with exposure to asbestos. "However, in previous analysis using plasma samples we could not confirm NEAT1 as circulating marker for mesothelioma (data not shown)." (PMID 32435497, 2020).
metastatic cancer (1 paper, 2025). A carcinoma which has spread from the original site of growth to another anatomic site. "Additionally, NUPR1 is linked to BM in LSCC, and NEAT1 is a potential metastatic cancer cell cycle participant." (PMID 39085744, 2025).
metastatic melanoma (1 paper, 2019). A melanoma that has spread from its primary site to another anatomic site. "The RT-PCR analysis revealed that the expression of NEAT1 was remarkably increased in all metastatic melanoma cell lines when compared with normal cells." (PMID 31462890, 2019).
mucinous adenocarcinoma (1 paper, 2022). An invasive adenocarcinoma composed of malignant glandular cells which contain intracytoplasmic mucin. "NEAT1 showed much higher expression in mucinous adenocarcinoma than adenocarcinoma(p < 0.01)." (PMID 36262350, 2022).
myocarditis (1 paper, 2025). Myocarditis is a condition that is characterized by inflammation of the heart muscle (myocardium). "In a mouse model of myocarditis, transfusion with Neat1-low dendritic cells (DCs) reduced the inflammatory response, while in a heart transplantation model, transfusion with Neat1-low DCs induced immune tolerance." (PMID 40362651, 2025).
nasal polyp (1 paper, 2025). "In vivo validation was performed using a mouse nasal polyp model, and molecular interactions among NEAT1, miR-199-3p, and PAK4 were confirmed via dual-luciferase reporter assays." (PMID 40661947, 2025). "NEAT1 promotes EMT in nasal polyp epithelial cells by modulating the miR-199-3p/PAK4 axis, highlighting its potential as a diagnostic biomarker and therapeutic target in CRSwNP." (PMID 40661947, 2025). "We first demonstrated that NEAT1 is significantly upregulated in both clinical CRSwNP specimens and an OVA/SEB-induced murine nasal polyp model." (PMID 40661947, 2025). "In our preliminary transcriptomic analysis of nasal polyp epithelial cells, we identified PAK4 (p21-activated kinase 4) as a potential downstream effector of NEAT1." (PMID 40661947, 2025).
neuropathy (1 paper, 2022). A disorder affecting the nervous system that manifests with pain, tingling, numbness, and/or muscle weakness. "NEAT1, which is located in the nuclear paraspeckles, has been reported to be involved in various biological processes, such as tumorigenesis, infection, neuropathy, and immunity." (PMID 35425712, 2022).
nonalcoholic fatty liver (1 paper, 2023). "The lncRNA NEAT1-MicroRNA-140 axis exacerbates nonalcoholic fatty liver by interrupting AMPK/SREBP-1 signaling." (PMID 37156995, 2023).
nuclear cataract (1 paper, 2020). A cataract (disease) that involves the lens nucleus. "Our previous studies have identified that NEAT1 expression was upregulated in human PCO-attached LECs compared with normal-attached LECs and increased in LECs obtained from patients with ASC compared with nuclear cataracts." (PMID 32596382, 2020). "Next, our previous studies have indicated that NEAT1 expression was upregulated by almost 7-fold in human PCO-attached LECs compared with normal-attached LECs and increased by nearly 6-fold in LECs obtained from patients with ASC compared with nuclear cataracts." (PMID 32596382, 2020).
ocular toxoplasmosis (1 paper, 2019). Ocular toxoplasmosis is an infection in the eye caused by the parasite, Toxoplasm a gondii. "In our results—obtained in human retinal Müller cells, which have direct relevance to ocular toxoplasmosis—LINC01105, BANCR, MIR17HG, MIR155HG, lnc-SGK1, MEG3, KCNQ1OT1, NEAT1, NeST, and MALAT1 were the most dysregulated lncRNAs with known immunologic activities." (PMID 31547203, 2019).
oligospermia (1 paper, 2025). Decreased number of spermatozoa in the semen. "In the severe oligospermia group, we noted a significant positive correlation between NEAT1 expression and levels of LH and FSH (r = 0.34, p = 0.04)." (PMID 40165339, 2025). "The data showed significant downregulation of NEAT1 in the severe oligospermia group compared to the fertile male group." (PMID 40165339, 2025). "In patients with severe oligospermia, serum NEAT1 levels were significantly lower than in healthy controls, with a median fold change of 0.52 (IQR: 0.15–0.95; p = 0.0476)." (PMID 40165339, 2025). "The significant positive correlation between NEAT1 expression and gonadotropin levels in severe oligospermia suggests that NEAT1 may enhance the hormonal environment supporting spermatogenesis." (PMID 40165339, 2025). "ROC curve analysis revealed that serum levels of NEAT1 can effectively differentiate patients with severe oligospermia from healthy individuals, achieving an AUC of 0.6989 (95% CI: 0.6148 to 0.9269, p = 0.01), with a sensitivity of 53% and specificity of 82% at a threshold greater than 0.53-fold." (PMID 40165339, 2025).
ovarian disorder (1 paper, 2025). A disease involving the ovary. "Dysregulation of non-coding RNAs, including lncRNAs (e.g., NEAT1, KCNQ1OT1), circRNAs, and pseudogenes, further underscores the multifactorial nature of these ovarian disorders." (PMID 40725447, 2025).
ovarian insufficiency (1 paper, 2025). "In studies of Premature ovarian insufficiency, lncRNA nuclear-enriched abundant transcript 1 (NEAT1) and STC2 are downregulated in POI mice, whereas miR-654 is upregulated in the plasma of POI patients." (PMID 40519517, 2025).
Pain (1 paper, 2023). An unpleasant sensory and emotional experience associated with actual or potential tissue damage, or described in terms of such damage. "Neat1 coordinated the expressions of diverse inflammatory genes known to cause microglial activation, which are critical for the pathology of peripheral neuropathic pain." (PMID 37614230, 2023).
pancreatic adenocarcinoma (1 paper, 2025). "Moreover, a notable negative relationship between the expression levels of NEAT1 and miR-129-5p of pancreatic adenocarcinoma samples (r= −0.234) was found based on ENCORI database." (PMID 40730640, 2025).
peripheral nerve injury (1 paper, 2020). Injury to a peripheral nerve. "In peripheral nerve injury, lncRNA-nuclear enriched abundant transcript 1 rich nuclear transcription factor 1 (NEAT1) promotes the proliferation and migration of Schwann cells by modulating the miR-34 a/SATB1 axis." (PMID 32323054, 2020).
pertussis (1 paper, 2023). A contagious bacterial respiratory infection caused by Bordetella pertussis. "The ceRNA network including miRNA-lncRNA-mRNA showed that lncRNA XIST and NEAT1 have the most important role among other lncRNAs in the network by affecting five common miRNAs related to human genes involved in staphylococcus aureus infection and pertussis." (PMID 37169818, 2023).
premature ovarian failure (1 paper, 2024). "NEAT1 is downregulated in premature ovarian failure (POF) mice, where it modulates the STC2/MAPK pathway to reduce apoptosis and autophagy." (PMID 39334761, 2024).
primary Sjögren’s syndrome (1 paper, 2021). "NEAT1 expression has been up-regulated in CD4+ and CD8+ T cells of patients with primary Sjögren’s syndrome." (PMID 34804042, 2021).
Recurrent aphthous stomatitis (1 paper, 2021). Recurrent episodes of ulceration of the oral mucosa, typically presenting as painful, sharply circumscribed fibrin-covered mucosal defects with a hyperemic border. "LncRNA NEAT1 promotes inflammatory responses, which contribute to recurrent aphthous stomatitis (RAS)." (PMID 34972503, 2021).
Salmonella Infections (1 paper, 2020). Infections with bacteria of the genus SALMONELLA. "Confirming the initiation of an epithelial immune response by the intestinal barrier model, Salmonella infection induced the expression of both coding (SOCS3, CXCL2, CXCL3) and noncoding (NEAT1) immune-associated RNAs in IECs." (PMID 32071273, 2020).
skin squamous cell carcinoma (1 paper, 2022). A carcinoma arising from the squamous cells of the epidermis. "This study is the first to demonstrate that the lncRNA NEAT1, as a ceRNA, affects the proliferation of skin squamous cell carcinoma cells through the miR-342-3p/CUL4B/PI3K-Akt signaling pathway." (PMID 35909905, 2022). "The expression of lncRNA NEAT1 in skin squamous cell carcinoma cell lines (A431, SCC13, HSC-5, and SCL-1) and human normal skin cell line HaCaT was further detected by real-time quantitative PCR." (PMID 35909905, 2022). "Fluorescence quantitative PCR was used to detect the expression of lncRNA NEAT1 and miR-42-3p in skin squamous cell carcinoma and adjacent tissues." (PMID 35909905, 2022).
temporal lobe epilepsy (1 paper, 2017). A localization-related (focal) form of epilepsy characterized by recurrent seizures that arise from foci within the temporal lobe, most commonly from its mesial aspect. "Furthermore, we show that while NEAT1 is acutely down-regulated in response to neuronal activity, repeated stimulation results in NEAT1 becoming chronically unresponsive in independent in vivo rat model systems relevant to temporal lobe epilepsy." (PMID 28054653, 2017). "First, we found that acute (1 and 7 days) pilocarpine-induced seizure activity, a well-established model of temporal lobe epilepsy [TLE27], significantly down-regulated NEAT1 expression, consistent with our findings in iPSC-derived neurons where NEAT1 was also down-regulated upon acute stimulation." (PMID 28054653, 2017).
temporomandibular joint disorder (1 paper, 2025). Any condition affecting the anatomic and functional characteristics of the temporomandibular joint. "A single Mito-Ru MOF treatment downregulates NEAT1 and inhibits the production of ROS, thereby reducing Freund’s adjuvant (CFA)-induced temporomandibular joint disorders (TMD)." (PMID 40362651, 2025).
thyroid nodule (1 paper, 2021). A small circumscribed mass in the THYROID GLAND that can be of neoplastic growth or non-neoplastic abnormality. "Next, analysis of suspicious thyroid nodules versus the contra-lateral tissue revealed that expression of MALAT1, HOTAIR, PVT1, and NEAT1 was significantly higher in malignant lesion than in contra-lateral normal tissue (P < 0.05)." (PMID 33030666, 2021).
tongue cancer (1 paper, 2025). A malignant neoplasm affecting the tongue. "This study enrolled 1192 individuals who were cancer-free and 400 Taiwanese male patients who had tongue cancer in order to investigate the connection between Neat1 polymorphisms and the emergence of tongue carcinogenesis." (PMID 40027195, 2025). "Our objective was to determine the associations between four Neat1 gene SNPs and clinicopathological traits linked to Taiwanese tongue cancer risk." (PMID 40027195, 2025). "This study establishes a link between the clinicopathological features of tongue cancer patients and Neat1 polymorphisms." (PMID 40027195, 2025). "We looked examined the effects of three variants in the Neat1 gene and clinicopathological characteristics on the risk of tongue cancer in 400 male Taiwanese patients who already had the disease." (PMID 40027195, 2025). "Long noncoding RNAs (lncRNAs) called nuclear enriched abundant transcript 1 (Neat1) are linked to tumor growth, survival, and apoptosis in a variety of cancer types; however, it is unclear how these factors relate to tongue cancer." (PMID 40027195, 2025). "This study is the first to establish a link between the clinicopathological features of tongue cancer patients and Neat1 polymorphisms." (PMID 40027195, 2025). "The Cancer Genome Atlas database noted that Neat1 mRNA levels are higher in tongue cancer patients compared to normal tissues and are associated with tumor stage and metastasis." (PMID 40027195, 2025). "This work, in our opinion, shows a significant association between Neat1 polymorphisms and tongue cancer in the Taiwanese population." (PMID 40027195, 2025). "Next, we examined the role of Neat1 gene polymorphisms on clinicopathologic characteristics of tongue cancer patients." (PMID 40027195, 2025). "Furthermore, it is unknown how Neat1 polymorphisms and clinicopathological traits in individuals with tongue cancer relate to one another." (PMID 40027195, 2025). "We next used the TCGA database to analyze Neat1 mRNA levels, tumor stage, and metastasis in tongue cancer patients." (PMID 40027195, 2025). "In the current human tongue cancer investigation using the TCGA database, Neat1 expression was found to be higher in tumor tissues compared to normal tissues." (PMID 40027195, 2025). "The Neat1 SNP rs3825071 may represent a potential biomarker for the clinical pathogenesis of tongue cancer." (PMID 40027195, 2025). "Additionally, Neat1 mRNA levels are higher in tongue cancer patients compared to normal tissues." (PMID 40027195, 2025). "Cigarette smoke may influence Neat1 functions, resulting in the protective effects of Neat1 SNPs being observed in non-smoking but not in smoking tongue cancer patients." (PMID 40027195, 2025).
tyrosinemia (1 paper, 2026). An autosomal recessive inherited metabolic disorder caused by mutations in the FAH, HPD, and TAT genes. "Correlation analysis revealed a positive association between NEAT1 expression and AST and ALP levels, whereas MALAT1 was inversely correlated with INR in the tyrosinemia group." (PMID 41736130, 2026).
uremia (1 paper, 2025). A clinical syndrome associated with the retention of renal waste products or uremic toxins in the blood. "In addition, NEAT1/miR-122-5p/Occludin axis, as a promising therapeutic target, will provide new ideas and methods for reducing complications and improving quality of life in patients with uremia." (PMID 40338929, 2025).
uveal melanoma (1 paper, 2019). A melanoma derived from melanocytes of the uveal tract.
vasculitis (1 paper, 2023). "The representative fundus images showed that more severe vasculitis, multiple chorioretinal lesions, and prominent inflammatory infiltration were observed in the fundus of control mice than that in Neat1-silenced mice." (PMID 37716986, 2023).
vitiligo (1 paper, 2020). Generalized well circumscribed patches of leukoderma that are generally distributed over symmetric body locations and is due to autoimmune destruction of melanocytes. "MS and vitiligo shared 37 differentially expressed (positive co-expressed) genes, all of which showed contradictory expressions exceptSPEN,NEAT1,MIR612,MALT1 andKMT2A (similar expression)." (PMID 33763205, 2020).